IDH1 (isocitrate dehydrogenase (NADP(+)) 1)
Diseases named in the same sentence as IDH1 in open-access papers (continued):
Sharing a sentence is not in itself a finding about the gene and the disease.
glioma (continued). "Moreover, LINC00324 expression was generally upregulated in IDH1 wild-type glioma patients with worse prognosis, suggesting that LINC00324 may be involved in the mechanism of glioma IDH mutation and tumor metabolic reprogramming." (PMID 38530810, 2024). "Therefore, amino acid radiotracer uptake for glioma grading may be more consistent in IDH1-wildtype than in IDH1-mutant tumors." (PMID 38932755, 2024). "On the other hand, in LN229, the lack of mutation in IDH1 implies a different genetic profile and therapeutic response compared to gliomas with IDH1 mutations, where it has been observed that this gene mutation sensitizes tumor cells to various chemotherapeutic agents." (PMID 39062770, 2024). "Although IDH1-mut was shown to block cell differentiation in tumors of different tissue origins, whether it hinders the differentiation of all 3 neural lineages in glioma remains controversial." (PMID 38662454, 2024). "However, while other mIDH gliomas demonstrated a CpG Island Methylator Phenotype (CIMP), these six tumors with secondary IDH1 mutations displayed the inverse pattern of methylation disturbance; a CpG Island Demethylator Phenotype (CIDP) in keeping with other RRD HGG." (PMID 39876890, 2024). "The increase in oleic acid could potentially be a compensatory mechanism, but even if it is, it is most likely a failed compensatory mechanism, as our data suggested that treatment with oleic acid-induced apoptosis and inhibited growth of the IDH1 MT glioma cell line." (PMID 39149696, 2024). "However, tumour-suppressing effect of PARP inhibitor is low in IDH1/2-wildtype gliomas." (PMID 38615034, 2024). "There are many features by which gliomas can be classified, but some of the main ones are considered to be classified by grade of malignancy (Grade I–IV) and by the presence of a mutation in the IDH1 gene (IDH1− and IDH1+), where IDH1− is also called “wild type” and IDH1+ is called “mutant type”." (PMID 38256907, 2024). "In this study, we designed an approach to compare the epigenetic and transcriptional phenotype of IDH1R132H and IDH1 wild-type mouse glioma models and how early stages of OPC gliomagenesis may provide insight into mechanisms of glial lineage specification that can be therapeutically exploited." (PMID 38334611, 2024). "Furthermore, high ZDHHC15 expression was significantly associated with worse prognosis in patients with IDH1 wild-type and mutant glioma, 1p/19q non-codeletion glioma, MGMT promoter methylated and non-methylated glioma, and primary and recurrent glioma." (PMID 37161425, 2023). "In this study, we sought to provide information on whether IDH1 gene status is closely related to the efficacy of radiotherapy in WHO grade 4 glioma patients by using statistics from the Chinese Glioma Genome Atlas (CGGA), The Cancer Genome Atlas (TCGA) and our own data." (PMID 37952042, 2023). "Furthermore, we established IDH1 mutant and wild-type glioma cells and assessed whether they differ in radiosensitivity and malignant biological properties." (PMID 37952042, 2023). "Finally, we concluded by making predictions and speculating that the CRNDE/miR-23b-3p/IDH1 network may potentially play a role in the advancement of glioma." (PMID 37934582, 2023). "A small multi-center clinical trial in patients with relapsed or refractory IDH1 mutated gliomas observed no dose-limiting toxicity and provided preliminary evidence for effective brain penetration and therapeutic efficacy of FT-2102, although these results need to be confirmed by further studies." (PMID 37049661, 2023). "However, most glial neoplasms, including GBM, lack the IDH1 mutation." (PMID 37568909, 2023). "Because gliomas contain substantial necrotic cell death, and also may be particularly sensitive to DC vaccine immunotherapy, they may be especially sensitive to IDH1- or IDH1R132H-mediated modulation of local T cells in the tumor." (PMID 37161052, 2023).
glioma (continued). "As DNA methylation may affect binding of TFs to specific motifs, we evaluated DNA methylation levels within c-Jun motifs and their flanking regions (c-Jun motif +/− 20 bp) in enhancers detected in gliomas with IDH1 wild type (IDHwt) or mutant (IDHmut) status from the Glioma Atlas." (PMID 36850002, 2023). "Three advantages to this system over most orthotopic patient-derived IDHmut glioma xenograft models are that it has (a) consistent, faster in vivo growth; (b) an immunocompetent microenvironment; and (c) control IDHwt cells that, aside from IDH1 R132H, are isogenic with control IDHmut glioma cells." (PMID 37104042, 2023). "A previous study demonstrated that IDH1 mutations result in the production of the onco-metabolite 2-hydroxyglutarate, and indicated that the excess 2-hydroxyglutarate contributes to the formation and malignant progression of ICC, gliomas, and chronic myelogenous leukaemia." (PMID 37076565, 2023). "Using recombinant wt IDH1 and the most common IDHvariant in gliomas,27−30 IDH1 R132H, our biochemical and biophysical studies surprisinglyreveal a clear disconnection between inhibitory selectivity and bindingaffinity of the mIDH inhibitors for wt and R132H IDH1." (PMID 36952395, 2023). "Thus, the ceRNA of lncRNA CRNDE/miR-23b-3p/IDH1 axis was formed, which may play an integral role in glioma progression." (PMID 37934582, 2023). "In addition, the bi-directional correlations between 5hmC modifications over promoter regions or gene bodies and gene expression were greatly disturbed in grade 4 gliomas regardless of IDH1 mutation status." (PMID 37580817, 2023). "Also, circMMD expression was significantly correlated with tumor grade and IDH1 status in gliomas." (PMID 36932454, 2023). "Accordingly, this comprehensive model based on four conventional sequences and three different ROIs of MR images, combined with clinical features, was able to reflect the heterogeneity of gliomas more comprehensively and completely and may have higher accuracy in predicting IDH1 gene status." (PMID 37354775, 2023). "The accumulated evidence suggests that maintaining 2-HG levels or IDH1 mutations may not be essential for glioma growth, as the loss of 2-HG or mutant IDH1 expression alone is insufficient to prevent tumor propagation." (PMID 37108511, 2023). "This suggests that CNS cancers with IDH1/ATRX deficiency are not subject to the same DNA lesions or repair processes as other CNS cancers and they may potentially belong to a separate patient subclass, though we could not identify evidence of this." (PMID 36883553, 2023). "Moreover, the coadministration of PD-L1 blockade with IDH1R132H inhibition and the standard of care (RT + TMZ) markedly enhanced the outcome of IDH1-mut glioma-bearing mice, counteracting T-cell exhaustion and eliciting an immunological memory with the generation of memory CD8+ T-cells." (PMID 35267433, 2022). "The inconsistency of IDH inhibitors’ preclinical data in gliomas may depend on the fact that most IDH1-mut glioma cell lines and xenografts are derived from grade III or grade IV tumors with acquired tertiary genetic alterations in the mitogenic signaling pathways." (PMID 35267433, 2022). "Therefore, GBM may selectively induce IDH1 mRNA, protein, and enzymatic activity to support high-grade glioma cells with macromolecules for rapid expansion." (PMID 35877430, 2022). "The detection of several molecular markers, including IDH1 mutation, 1p/19q codeletion, MGMT promoter methylation status has been applied with clinical diagnoses of gliomas, we analyzed whether LMO1 expression was correlated with some molecular genetic characteristics by using CGGA database." (PMID 35280742, 2022). "The high-grade glioma cell lines used in our study do not harbor mutations in the IDH1/2 genes." (PMID 35406561, 2022).
glioma (continued). "In conclusion, this meta-analysis highlights that there are specific molecular (such as IDH1 mutations and 1p19q LOH) and pathological features and a better prognosis in CIMP-positive gliomas, suggesting that CIMP could be used as an independent prognostic marker for glioma." (PMID 36181110, 2022). "Also, 414 genes were identified to be downregulated in advanced stage gliomas and be upregulated in IDH1-mutant gliomas, indicating that these genes may act as tumor suppressors in inhibiting glioma progression." (PMID 35341001, 2022). "This immune signature may contribute to the diagnosis and treatment of IDH1-mt gliomas." (PMID 36159801, 2022). "Finally, the relationship between the immunohistochemical index of IDH1, Ki-67 expression, and the peripheral serum lymphocyte count in glioma grading is unknown." (PMID 36147928, 2022). "In gliomas, the IDH1 mutation has a negative impact on the immune system resulting in reduced Natural Killer ligands and decreased tumor lysis, as well as decreased chemokines CXCL9, CXCL10 with subsequent reduction in the number of CD3+ CD8+ tumor infiltrating lymphocytes." (PMID 35664748, 2022). "In addition, high levels of TRIM22 were linked to IDH1-wild type and ATRX-wild type gliomas." (PMID 36139694, 2022). "Hence, it can be inferred that reduced CXCL10 secretion may be heavily involved in IDH1-mutant glioma cells’ strategy to hamper CD8+ T cell chemotaxis." (PMID 35385679, 2022). "Isocitrate dehydrogenase 1 (IDH1) and isocitrate dehydrogenase 2 (IDH2) are commonly mutated in most low-grade gliomas and secondary glioblastoma multiforme, and IDH mutation status is a feature of glioma subclassifications in the 2016 World Health Organization classification." (PMID 35501312, 2022). "Our study revealed that in IDH1 R132H-negative gliomas, EZH2 overexpression predicted significantly poorer PFS and OS outcomes with a higher recurrence risk (p = 0.001) and 4.7 times higher mortality (p = 0.025) than IDH1 R132H-negative gliomas with low EZH2 expression." (PMID 36292072, 2022). "IDH1/2 mutations have been found in glioma, acute myelogenous leukemia (AML), chondrosarcoma, cholangiocarcinoma, and T-cell angioimmunoblastic lymphoma, as well as in colorectal and prostate cancers, with IDH1 R132H and IDH2 R140Q the frequently observed mutations." (PMID 36710884, 2022). "Therefore, GBM may selectively induce IDH1 mRNA, protein, and enzymatic activity to support high-grade glioma cells with macromolecules for rapid expansion via these genes and pyruvate metabolism." (PMID 35877430, 2022). "Additionally, in order to find out about the nature of this phenomenon, the authors analyzed the glow intensity of two glioma cell lines in vitro: NHAE6E7hTERTIDH1mut, which was transformed by mutant IDH1, and NHAE6E7hTERTRas, which was transformed by H-Ras (wild-type IDH1 model)." (PMID 35055109, 2022). "Finally, 1209 genes were identified to be upregulated in advanced stage gliomas and be downregulated in IDH1-mutant gliomas, indicating that these genes may act as oncogenes in promoting glioma progression." (PMID 35341001, 2022). "Thus, reduced immune infiltrates in mutant IDH1 glioma could play a role in the aggressiveness differences between mutant and wild-type gliomas." (PMID 35269652, 2022). "Alterations in metabolism-related genes, such as IDH1 mutation, O6-methylguanine-DNA methyltransferase gene (MGMT) promoter methylation, or epidermal growth factor receptor (EGFR) amplification, are frequent in glioma patients and are closely related to prognosis." (PMID 36248907, 2022). "Therefore, extensive surgical tumor removal is essential to improve the prognosis of patients with WHO grade III gliomas, especially for astrocytic tumors with the IDH1/2 mutation lacking the 1p/19q co-deletion." (PMID 35645972, 2022).
glioma (continued). "Besides, according to IDH mutation status, gliomas can be classified into IDH1 wild-type, IDH1-mutant and NOS (meaning that there is not enough information to define the entity)." (PMID 34422904, 2021). "Therefore, inhibition of glutaminase slowed down the growth of IDH1-mutant glioma cells." (PMID 34356864, 2021). "However, this high rate of visible fluorescence in IDH1 wildtype tumors might be explained by the high number of WHO grade IV gliomas with IDH1 wildtype included in this analysis." (PMID 34395266, 2021). "Indeed, the currently most successful therapeutic approach based on metabolic reprogramming regards the inhibitors of the mutant IDH1/2, which are being used to treat acute myeloid leukemia patients, as well as gliomas and other solid cancers, such as cholangiocarcinoma and chondrosarcoma." (PMID 34771610, 2021). "Moreover, the association between BCAT1 and IDH1 status was also confirmed, as previously reported, high expression of BCAT1 is observed in IDH1 wild-type gliomas but is also preferentially expressed in non 1p19q co-deleted gliomas." (PMID 33493139, 2021). "Compared with high-grade glioma, patients with low-grade glioma (LGG) have a significantly higher incidence of epilepsy, which may be related to the slower growth rate and higher IDH-1 mutation frequency of LGG." (PMID 34336837, 2021). "In contrast, IDH1 mutant gliomas are known for longer survival and may be stable for years." (PMID 34631582, 2021). "However, little is known about whether combined IDH1 mutation and SVZ involvement are clinically relevant and provide improved prognostic performance for patients with glioma." (PMID 34490090, 2021). "Therefore, the identification of IDH1 gene status in gliomas patients might be helpful for tumor grading and further treatment." (PMID 33795525, 2021). "In an in vitro experiment, after treatment with TMZ, the α-ketoglutarate and glutamate levels were found to be significantly lower than those in untreated glioma cells, indicating that 1H MRS may be a potential assessment tool for assessing the response to TMZ treatment in IDH1-mutant gliomas." (PMID 34422648, 2021). "Besides, IDH1 and IDH2 mutations are early events in the development of gliomas." (PMID 34961815, 2021). "Furthermore, glioma samples (both LGGs and GBM) with an IDH1-mutant type have lower risk scores than IDH1wild-type samples, and the risk scores in LGGs with IDH1-mutant and 1p/19q codeletion samples have lower risk scores than IDH1-mutant and 1p/19q non-codeletion samples." (PMID 33732284, 2021). "Second, only one molecule, IDH1, was considered in this study, but many other molecules status such as 1p/19q codeletion and O6-methylguanine-DNA methyltransferase promoter methylation also play an important role in the development of gliomas, which needs to be further investigated." (PMID 34880724, 2021). "Interestingly, noncanonical IDH1 mutations have been identified with a higher frequency in AYA gliomas compared to the adult patient population." (PMID 34587990, 2021). "Thus, NADPH levels are diminished in IDH1-R132H gliomas in situ." (PMID 34070746, 2021). "This is consistent with recent reports that glioma cells are defective in NAD+ biosynthesis, especially for those with IDH1 somatic mutations and suggests a major factor in the regulation of PARP1 signaling in GSCs and glioma cells may be related to a defect in NAD+ biosynthesis." (PMID 34806016, 2021).
glioma (continued). "Besides, IDH1 mutant glioma samples were enriched in cluster 2 (p < 0.05)." (PMID 34211979, 2021). "Moreover, in patients with non-SVZ-contacting glioma, IDH1 mutation concurrent with tumor-SVZ distance >10 mm has better OS and PFS." (PMID 34490090, 2021). "Therefore, abrogation of CCNF expression facilitates IDH1-R132H-mediated tumorigenesis and metastasis in glioma; that is, CCNF may serve as a tumor suppressor in glioma." (PMID 34397798, 2021). "Non-canonical IDH1R132X occurs in 8% of lower-grade glioma harboring IDH1 hotspot mutations." (PMID 34440884, 2021). "Besides that, MYD88 was also down regulated in the IDH1 mutant gliomas." (PMID 33898320, 2021). "Glioma patients with IDH1 mutation have median OS three times longer than those without, codeletion of 1p and 19q is associated with better survival rates in glioma, and thus, low CD44 expression patients with glioma may have better clinical outcomes." (PMID 35187044, 2021). "For instance, low-grade gliomas have been classified according to the 1p and 19q loci co-deletion as well as the mutations in the IDH1 and IDH2 genes; tumors without these alterations have been shown to be clinically and molecularly similar to high-grade tumors." (PMID 34868236, 2021). "We previously presented a deterministic cell state model of mutant isocitrate dehydrogenase-1 (IDH1) gliomas that consisted of quiescent, stem and differentiated glioma cells that could transition between each other reflecting intratumoral heterogeneity (ITH) and cellular adaptation." (PMID 34424912, 2021). "Moreover, increased expression of Neural G0 genes was associated with better patient prognosis, negatively correlated with the proliferative state in gliomas, and was independent of tumor grade and IDH1/2 mutation status." (PMID 34101353, 2021). "The results of this preliminary study in a small patient population suggest that the fractal dimension using MET PET in patients with newly diagnosed gliomas is useful for differentiating glioma, especially in relation to IDH1 mutation status, which has not been possible with SUV parameters." (PMID 34743250, 2021). "In our exploration, we found out that by combining IDH1 mutation with ATRX mutation, gliomas in the low-risk group could be further divided into three subtypes: LowRisk_IDH1wt, LowRisk_IDH1mut/ATRXmut and LowRisk_IDH1mut/ATRXwt with obvious survival difference." (PMID 34093830, 2021). "In addition, B2M levels in IDH1 mutant glioma (weak intensity 58.7%; moderate intensity 37%; strong intensity 4.3%) samples were lower than those in IDH1 wild‐type (weak intensity 14%; moderate intensity 40.4%; strong intensity 45.6%) samples(Z = −5.534, p < 0.01)." (PMID 33960680, 2021). "Notably, these survival data are independent of the mutation status of IDH1, which is mutated in 78% of patients in the lower grade glioma cohort and 6% of the GBM cohort." (PMID 33478100, 2021). "This is more likely to be a model for IDH1/2 gliomas, which may originate from adult stem cells." (PMID 34948008, 2021). "Besides, high BCAT1 expression represents poor survival of IDH1 wild-type gliomas." (PMID 33493139, 2021). "Therefore, STMN3 is a consistent eQTL for rs3761124 in early neurological development, in the normal adult brain and in glioma or during gliomagenesis, whereas the RTEL1 expression correlated with rs3761124 only during early neurological development and in IDH1 wild‐type glioma." (PMID 33169458, 2021). "IDH1 and IDH2 mutations (hereafter referred to as IDH mutation) are mutually exclusive “truncal mutations”, which are frequently associated with better prognoses for gliomas, such as Grade II and Grade III gliomas, and thereby considered as prognostic factors for gliomas." (PMID 34298824, 2021). "In addition, five of 45 IDH1-R132H-negative gliomas were oligodendrogliomas, which carried non-canonical IDH1/2 mutations (1 IDH1-R132L, 4 IDH2-R172 Mut)." (PMID 34020723, 2021).